SIRT6 (sirtuin 6)
Diseases named in the same sentence as SIRT6 in open-access papers (continued):
Sharing a sentence is not in itself a finding about the gene and the disease.
breast cancer (59 papers, 2013 to 2026). A primary or metastatic malignant neoplasm involving the breast. "This evidence indicates that TBX3 has a tumor suppression function and its loss phenocopies SIRT6 amplification in HER2-positive breast cancer." (PMID 38081972, 2023). "Low SIRT6 expression was associated with a better OS in breast cancer (HR = 0.49, 95% CI = 0.27–0.89, P = 0.179), but was associated with a worse OS in gastrointestinal tumours (HR = 0.30, 95% CI = 0.10–0.91, P = 0.069)." (PMID 35172823, 2022). "In the case of SIRT6, low SIRT6 expression was associated with poor overall survival in the hormone-receptor positive subtype, however, SIRT6 was reported to be up-regulated in breast cancer tissues but the changes were statistically insignificant." (PMID 33684691, 2021). "In breast cancer cells, high levels of SIRT6 are associated with resistance to epirubicin and paclitaxel." (PMID 33800266, 2021). "With respect to a tumor-suppressive role of SIRT6, the loss of SIRT6 stimulated the progression of hepatocellular carcinoma, and lower expression of SIRT6 was associated with poor prognosis in breast cancer patients." (PMID 34359939, 2021). "Overexpression of SIRT6 in breast cancer cells increased proliferation, but mutation at the CK2 Ser-338 phosphorylation site of SIRT6 inhibited the proliferation of breast cancer cells." (PMID 33027921, 2020). "In breast cancers, both the nuclear and cytoplasmic expression of SIRT6 were associated with shorter survival of patients." (PMID 30524965, 2018). "In breast cancer cells, SIRT6 expression was associated with increased expression of MMP, cyclin D1, and NFκB, and was involved in nuclear localization of β-catenin." (PMID 30524965, 2018). "And consistent with our previous report that SIRT6 expression is associated with active β-catenin expression in breast cancer cells, SIRT6 expression was associated with increased expression of active β-catenin and invasiveness of ovarian cancer cells." (PMID 30524965, 2018). "Immunohistochemical expression of SIRT6 was associated with favorable prognosis of breast cancer patients, and SIRT6 knockout was associated with shorter survival of hepatocellular carcinoma patients." (PMID 30524965, 2018). "Increased SIRT6 expression has been reported in pancreatic, prostate and breast cancers, where high SIRT6 levels are associated with chemotherapy resistance and poor prognosis." (PMID 25085992, 2014). "Among the sirtuins, SIRT1 and SIRT6 have been identified in EVs associated with breast cancer." (PMID 40214422, 2025). "Moreover, low SIRT6 expression was recently found to be associated with better overall survival of patients with breast cancer." (PMID 36291902, 2022). "However, other studies have shown that SIRT6 is highly expressed in skin cancers, breast cancers and prostate cancers and is associated with poor prognosis." (PMID 35915188, 2022). "CK2-mediated phosphorylation of SIRT6 is therefore implicated in the progression of breast cancer." (PMID 36009534, 2022). "High SIRT6 expression is associated with adverse prognosis in breast cancer (BC) patients." (PMID 33482921, 2021). "However, controversially, higher expression of SIRT6 was associated with favorable prognosis of breast cancer patients, and loss of SIRT6 was associated with progression of hepatocellular carcinomas and colon carcinomas." (PMID 33198792, 2020). "Consistent with this, immunohistochemistry results from different breast cancer subtypes showed that high SIRT6/1 levels are associated with constitutive high FOXO3 expression which is related to FOXO3 deregulation/inactivation and poor prognosis in breast cancer patient samples." (PMID 31357743, 2019). "In addition, high expression of SIRT6 was associated with lymph node metastasis of colorectal cancers and thyroid papillary carcinomas and was associated with poor prognosis of breast cancer, ovary cancer, gastric cancer, lung cancer, and diffuse large B-cell lymphoma patients." (PMID 33198792, 2020).
breast cancer (continued). "In addition, loss of SIRT6 was associated with resistance to trastuzumab in breast cancer cells." (PMID 30524965, 2018). "In a mouse model, MB-231 human breast cancer cell xenografts grow more slowly when Sirt6 expression is silenced." (PMID 41530841, 2026). "Numerous tumor tissues, such as those from colon cancer, breast cancer, ovarian cancer, hepatocellular carcinoma, osteosarcoma, prostate cancer, and renal cell carcinoma, exhibit increased expression of Sirt6, a Sirt family member." (PMID 41530841, 2026). "Accumulating evidence highlights SIRT6 as a critical regulator of breast cancer pathogenesis, exhibiting context-dependent roles across different subtypes." (PMID 41463311, 2025). "Collectively, these findings underscore the dual tumor-promoting and tumor-suppressive functions of SIRT6 in breast cancer and suggest that therapeutic strategies must consider tumor subtype and context." (PMID 41463311, 2025). "SIRT6 expression is upregulated in breast cancer, pancreatic cancer, primary melanoma, and non-small cell lung cancer, suggesting a pro-oncogenic role in these cancers." (PMID 38548549, 2024). "The role of SIRT6 in tumorigenesis and development remains controversial, although it can act as an oncogene in breast cancer, prostate cancer, HCC, and diffuse large B-cell lymphoma by inducing cancer cell proliferation, metastasis, and chemoresistance." (PMID 39408693, 2024). "Here, we identified TBX3 as a target downregulated by SIRT6 in both Delta16HER2- and HER2-positive breast cancer models, and we found that concomitant high SIRT6 and low TBX3 expression predicts poor prognosis in HER2-positive breast cancer patients." (PMID 38081972, 2023). "Accordingly, a sub-set of HER2-positive breast cancer patients with concurrent SIRT6-OE has a significant poorer relapse-free survival (RFS) probability than patients with low expression of SIRT6." (PMID 38081972, 2023). "Our work indicates that high levels of SIRT6 are indicative of poor prognosis and high risk of metastasis in HER2-positive breast cancer and suggests further investigation of TBX3 as a downstream target of SIRT6 and co-marker of poor-prognosis." (PMID 38081972, 2023). "As several novel small molecule activators and inhibitors of SIRT6 are becoming available, future pharmacological studies will be of pivotal importance to elucidate the role of SIRT6 and will help identify suitable breast cancer subtype-specific interventions." (PMID 38081972, 2023). "AKT1 phosphorylates SIRT6 at S338 and enhances the degradation of SIRT6 through the ubiquitin-proteasome pathway in breast cancer cells." (PMID 37607939, 2023). "We found that HER2-positive breast cancers (n = 680) have a higher median SIRT6 expression (p = 0.0322) than HER2-negative tumors (n = 4068)." (PMID 38081972, 2023). "In the context of HER2-amplified breast cancer, either TBX3 loss-of-function or SIRT6 amplification predicts a worse survival than patients with no alterations in SIRT6 and TBX3 (Log-rank P = 0.0007)." (PMID 38081972, 2023). "Such double-faced behavior of SIRT6 is particularly evident in heterogeneous diseases like breast cancer, which is characterized by distinct tumor subtypes." (PMID 38081972, 2023). "Our results point to a breast cancer subtype-specific effect of SIRT6 and warrant future studies dissecting the mechanisms of SIRT6 regulation in different breast cancer subtypes." (PMID 38081972, 2023). "It has also been reported that Runx2 negatively regulates SIRT6 expression at both the transcriptional and posttranslational levels in breast cancer." (PMID 34793336, 2022). "This study suggests that SIRT6 is a novel target molecule for the prevention of breast cancer invasion and metastasis." (PMID 35840633, 2022). "Our findings support further efforts to investigate these enzymes, especially ACLY, SIRT1, and SIRT6 for breast cancer diagnosis and therapy." (PMID 35203617, 2022).
breast cancer (continued). "Meanwhile, compared to the Sirt6+/+ mice, in vivo dada showed that Sirt6 deletion repressed mammary tumor development and increased survival in Sirt6+/− mice." (PMID 35927590, 2022). "Notwithstanding, more studies are required to investigate the expression level of SIRT6 and its effect on the metabolic profile of breast cancer at various stages of carcinogenesis." (PMID 36291902, 2022). "4H-Chromen, an activator of SIRT6, has been studied in various breast cancer cells and demonstrated to decrease cell proliferation in TNBC cells." (PMID 35203617, 2022). "While determining the involvement of SIRT6 in breast cancer cell migration, SIRT6 knockdown was found to reduce TPA- or TNF-α-induced cell migration in both cell lines." (PMID 35840633, 2022). "The results obtained in the present study revealed that SIRT6 is involved in the modulation of breast cancer cell invasion and migration by regulating MMP-9 expression in MCF-7 and MDA-MB-231 cells." (PMID 35840633, 2022). "In breast cancer cells, SIRT6 has been related to the upregulation of MMP-920, and SIRT6 knockdown has been shown to reduce MMP-9 expression." (PMID 35840633, 2022). "SIRT6 is found to be upregulated in hepatocellular carcinoma, breast cancer, ovarian cancer, esophageal cancer, lung cancer, osteosarcoma, papillary thyroid cancer, and prostate cancer." (PMID 35686673, 2022). "This study investigated the effect of SIRT6 on the invasive behavior of two breast cancer cell lines, MCF-7 and MDA-MB-231, as well as the role played by MMP-9." (PMID 35840633, 2022). "SIRT6 promotes breast cancer by regulating the acetylation and sensitivity to lapatinib of Forkhead box protein O3 (FoxO3)." (PMID 35172823, 2022). "In conclusion, SIRT6 regulated the migration and invasion of breast cancer cells in vitro and played an essential role in TPA- or TNF-α-induced MMP-9 expression." (PMID 35840633, 2022). "It is known that CSNK2A1 promotes proliferation and invasiveness of breast cancer cells through mediating phosphorylation of SIRT6." (PMID 36050449, 2022). "Although the involvement of SIRT6 in tumorigenesis has been frequently reported, only a small number of studies have addressed its role in breast cancer metastasis." (PMID 35840633, 2022). "The proliferative effects of SIRT6 have been explored in breast cancer, melanoma, and esophageal cancers." (PMID 35686673, 2022). "Breast cancer cell lines were also treated with vehicle or 4H-chromen and the results indicated that SIRT6 levels remained relatively constant displaying statistically insignificant changes in cell lines." (PMID 33684691, 2021). "UQCRFS1, COX5B, and NDUFB8 expression was blunted by both SIRT6 silencing in MDA-MB-231 cells and by the Sirt6 heterozygous deletion in mouse mammary tumors." (PMID 33482921, 2021). "In this study we showed variation of SIRT6 mRNA gene expression levels in a panel different breast cancer cells." (PMID 33684691, 2021). "ELF5 was identified as an acetylated protein in breast cancer cells and later shown to be subject to regulation by the acetyltransferases p300 and the deacetylase SIRT6." (PMID 33742100, 2021). "Curiously, a previous study evaluated the effect of SIRT6 overexpression (using Sirt6BAC mice) in the MMTV-PyMT mammary tumor model and found that SIRT6 overexpression also has the ability to hamper tumor progression in mice." (PMID 33482921, 2021). "The effect of SIRT6 on the proliferation of MDA-MB-231 breast cancer cells was the opposite in two studies." (PMID 34359939, 2021). "Dysregulation of SIRT6 is widely observed in different breast cancer subtypes; however, the role and function of SIRT6 in cancer development remain largely unexplored." (PMID 33684691, 2021). "Overall, our results clearly indicate that reducing Sirt6 expression slows mammary cancer development in the mouse MMTV-PyMT BC model." (PMID 33482921, 2021).
breast cancer (continued). "In support of this view, a positive correlation between ELF5 and SIRT6 was found in 48 breast cancer clinical samples by immunohistochemical staining." (PMID 33742100, 2021). "The heterozygous Sirt6 deletion resulted in a decreased Sirt6 protein expression in mammary tumor masses isolated from MMTV-PyMT+/−; Sirt6+/− animals as compared to the control mice." (PMID 33482921, 2021). "SIRT6 act as a tumor suppressor in several cancers, including pancreatic cancer, breast cancer, and hepatocellular carcinoma." (PMID 32158696, 2020). "In contrast, knock-down of SIRT6 increased viability of breast cancer cells treated with trastuzumab." (PMID 33198792, 2020). "In contrast, Sirt6 has been reported to be oncogenic in breast cancer, prostate cancer, hepatocellular carcinoma, and skin cancer." (PMID 32711549, 2020). "Even with the same MDA-MB-231 breast cancer cells, there are conflicting reports of SIRT6 either increasing or decreasing the proliferation of these cells." (PMID 33198792, 2020). "Immunohistochemical staining results also show that FOXO3 expression correlates positively with SIRT6/1 levels in different breast cancer subtypes." (PMID 31357743, 2019). "Evidence has been given to the survival of breast cancer patients with the abundance of SIRT6 and inversely correlated with induced protein degradation by chemical alterations in SIRT6 specific residues." (PMID 31591350, 2019). "Trastuzumab targets a specific receptor common in some breast cancers types, and the results showed that SIRT6 knockdown increased the survival of a resistant breast cancer cell line exposed to trastuzumab." (PMID 31591350, 2019). "To investigate this finding further, we studied the relationships between FOXO3, SIRT1 and SIRT6 expression by immunohistochemistry in a cohort of patients of different breast cancer subtypes." (PMID 31357743, 2019). "In a similar study, the role of SIRT6 in both epirubicin and paclitaxel resistance in breast cancer was identified." (PMID 31591350, 2019). "The tumor suppressor FoxO3a increases its levels of acetylation in mouse embryonic fibroblasts depleted of SIRT6, whereas its induction by epirubicin is attenuated in breast cancer cells overexpressing SIRT6." (PMID 31591350, 2019). "SIRT6 depletion increased chemotherapeutic agents sensitization in prostate cancer, breast cancer, and non-small cell lung cancer." (PMID 29563873, 2018). "Our data show that prolonged treatment of luminal breast cancer cells with AKT inhibitors induces FOXO3a dephosphorylation, nuclear translocation, and disrupts its association with SirT6, eventually leading to FOXO3a acetylation as well as BRD4 recognition." (PMID 30518851, 2018). "The knockdown of SIRT6 increased tumorigenesis and trastuzumab resistance in breast cancer while sensitizing cells to paclitaxel and epirubicin." (PMID 27824900, 2016). "SIRT6 has been implicated as a pro-metastatic factor, particularly in HER2-positive breast cancer." (PMID 41471349, 2025). "SIRT6 is carcinogenic in prostate cancer, skin cancer and breast cancer." (PMID 39479446, 2024). "SIRT6 regulates cancer metabolism by modulating both single- and double-stranded DNA break repair pathways and inflammation, promotes genomic stability and facilitates breast cancer progression." (PMID 39479446, 2024). "Altogether, these data suggest that TBX3 suppression or loss mimics SIRT6-OE and amplification in HER2-positive breast cancer and demands for further future specific investigations about their interaction/co-regulation and their role in therapy resistance, relapse and lung metastasis." (PMID 38081972, 2023). "To determine whether SIRT6-OE is relevant for HER2-positive breast cancer patients, we interrogated publicly available datasets using cBioPortal and GOBO databases." (PMID 38081972, 2023).
breast cancer (continued). "The reasons for these observations are not fully explained, but these findings may indicate the opposite roles of SIRT6 at different stages of BC carcinogenesis and in different types of breast cancer." (PMID 38203666, 2023). "Our work suggests that SIRT6 acts as a tumor oncogene in HER2-positive breast cancer." (PMID 38081972, 2023). "Despite the need for more work to help refine these aspects, to our knowledge this is the first study investigating the effect of SIRT6-OE on Delta16HER2-dependent mammary tumorigenesis and reporting a breast cancer subtype-specific, pro-tumorigenic role for this sirtuin." (PMID 38081972, 2023). "Accordingly, Kaplan–Meier plots from GOBO show that basal-like breast cancer patients with high expression of SIRT6 (red line, n = 70) have better prognosis in terms of RFS (Log-rank test, p = 0.04656) than patients expressing low levels of SIRT6 (grey line, n = 73)." (PMID 38081972, 2023). "To confirm whether SIRT6-OE is sufficient to induce TBX3 downregulation, we ectopically overexpressed SIRT6 in the human HER2 + /Delta16HER2 + breast cancer cell line BT474." (PMID 38081972, 2023). "This description perfectly fits not only our preclinical data, but also what we observed in patients, where high expression of SIRT6 correlates with a significantly worse prognosis of HER2-positive breast cancer patients, in particular those with grade 3 tumors." (PMID 38081972, 2023). "However, SIRT6 is elevated in cancers involving prostate cancer or breast cancer and is available to exert a role as an oncogene." (PMID 36159576, 2022). "The result showed variation on SIRT6 expression between different breast cancer cells lines." (PMID 33684691, 2021). "However, a previous study reported that SIRT6 overexpression inhibits cancer stem-like capacity in breast cancer with PI3K activation." (PMID 34225779, 2021). "Finally, SDH was not affected by either SIRT6 silencing in MDA-MB-231 cells or by Sirt6 deletion in mouse mammary neoplasms." (PMID 33482921, 2021). "However, controversially, poor prognosis of cancer patients having a higher expression of SIRT6 has been reported in various human cancers, such as breast cancer, gastric cancer, lung cancer, osteosarcoma, and ovarian cancer." (PMID 34359939, 2021). "The SIRT6 gene expression profiles in the different breast cancer cells were investigated." (PMID 33684691, 2021). "The aim of this study was to identify novel compounds targeting SIRT6 which may provide a new approach in development of anti-cancer therapy for breast cancer." (PMID 33684691, 2021). "We also showed the unique SIRT6 profile in distinct breast cancer cells." (PMID 33684691, 2021). "However, controversially, elevated expression of SIRT6 inhibited the proliferation and invasiveness of osteosarcoma cells, and breast cancer cells." (PMID 33198792, 2020). "In addition, SIRT6 stimulated the invasiveness of cancer cells by activating the epithelial-to-mesenchymal transition pathway in breast cancer, ovarian cancer, lung cancer, and osteosarcoma cells." (PMID 33198792, 2020). "Taking everything into consideration, their study shows that CK2 and SIRT6 are indicators of poor prognosis for breast carcinomas and that CK2-catalyzed phosphorylation of SIRT6 might be involved in the progression of breast carcinoma." (PMID 33027921, 2020). "Furthermore, in a second phase of the study, trastuzumab sensitivity in a resistant breast cancer cell line was correlated to SIRT6 abundance in cells." (PMID 31591350, 2019). "In breast cancers, SIRT6 increased both the proliferation and invasiveness of cancer cells." (PMID 30524965, 2018). "In addition, in breast cancers, one of the most common cancers in women, the role of SIRT6 has been controversially reported." (PMID 30524965, 2018). "In breast cancer, contradictory roles of SIRT6 in drug sensitivity have been reported." (PMID 27824900, 2016).